EZH2 (enhancer of zeste 2 polycomb repressive complex 2 subunit)
Diseases named in the same sentence as EZH2 in open-access papers (continued):
Sharing a sentence is not in itself a finding about the gene and the disease.
prostate carcinoma (continued). "The Polycomb protein enhancer of zeste homolog 2 (EZH2) has critical roles in prostate cancer (PCa) progression and drug-resistance, which remains an obstacle for PCa treatment." (PMID 34776951, 2021). "The ability of AR to repress transcription in LNCaP prostate cancer cells is related among other factors to cooperation with EZH2 histone-modifying enzyme, a component of the polycomb repressor complex 2 (PRC2)." (PMID 33430890, 2021). "The lncRNAs capable of regulating EZH2-catalzyed H3K27me3 and its possible effects on miR-340/miR-143/miR-145 expression in prostate cancer cells deserve further investigations." (PMID 33589600, 2021). "We observed that both GSK343 and γ-Oryzanol promoted miR-340-5p, miR-145-5p, and miR-143-3p expression in prostate cancer cells, showing the regulation of miR-340-5p, miR-145-5p and miR-143-3p expression by EZH2 and DNMT3a." (PMID 33589600, 2021). "In mouse and human prostate cancer organoids models, inhibition of EZH2 increased the expression of the Th1 attracting-chemokines CXCL9 and CXCL10 and derepressed endogenous double-strand RNA (ds RNA) expression." (PMID 34262562, 2021). "More importantly, recent study showed that EZH2 activation contributed to the silencing of miRNA expression in prostate cancer cells, such as miR-101-3p and miR-138-5p17." (PMID 33589600, 2021). "Relatedly, EZH2 and BMI1 double-positive prostate carcinomas are associated with metastasis with an increasing likelihood of therapy failure and disease relapse." (PMID 33804165, 2021). "Several substrates contributed to invasion and migration regulated by USP7, such as EZH2 in prostate cancer, and LSD1 in glioblastoma." (PMID 34469054, 2021). "The effective doses were first tested in a proliferating prostate cancer cell line (PC3) in which EZH2 was shown to be active." (PMID 34502238, 2021). "Other targets that have been associated with prostate cancer metastasis (or progression) include BIRC5/survivin, EZH2, TOP2A, HMMR, LPL, and SSTR1." (PMID 34680307, 2021). "Luteolin can inhibit H3K27me3 and downregulate the expression of EZH2 in human prostate cancer DU145 cells in a concentration-dependent manner." (PMID 34235089, 2021). "For example, in prostate cancer, N-Myc was found to induce enhancer of zeste homologue 2 (EZH2)-mediated transcription program." (PMID 34298815, 2021). "This is particularly relevant as a number of clinical trials using EZH2 inhibitors are currently in progress, including many in prostate cancer (NCT03480646, NCT04179864, NCT03460977)." (PMID 34099734, 2021). "EZH2 inhibition in murine prostate cancer cell lines with DZNep and EPZ also resulted in a drastic upregulation of Th1 cytokines TNF-α, IL-2 and IL-12." (PMID 34262562, 2021). "Here, the authors integrate a transcriptomics atlas of prostate cancer and validate it with preclinical models and single-cell RNA-seq, revealing the role of EZH2 and macrophage polarisation in tumour progression." (PMID 34857732, 2021). "Research had reported that human EZH2 was upregulated in different kinds of tumors like breast cancer, prostate cancer, and osteosarcoma (OS)." (PMID 34737956, 2021). "As EZH2 had been shown to interact with several lncRNAs, such as HOTAIR and PCAT-1, it was unclear which lncRNA was important for EZH2-driven prostate cancer progression." (PMID 33803328, 2021). "Ebastine, a marketed antihistamine drug, reduces EZH2 transcript levels, leading to decreased H3K27me3 levels in breast and prostate cancer cell lines." (PMID 34617019, 2021). "These investigations convincingly proved the mediating roles of the miRNA-DNMT3a feedback loop in SChLAP1/EZH2-induced prostate cancer pathogenesis." (PMID 33589600, 2021). "It is believed that the FOXO1 gene is a new inhibitory target of EZH2 and FOXO1 is a key mediator of EZH2 inhibition and induction of prostate cancer cell death." (PMID 34149432, 2021).
prostate carcinoma (continued). "A new inhibitory target and FOXO1 is a key mediator of EZH2 inhibition to induce prostate cancer cell death." (PMID 34149432, 2021). "For example, RUNX1 promoter is regulated by EZH2 (enhancer of zeste homolog 2)-dependent histone H3 lysine 27 (K27) trimethylation in prostate cancer cells." (PMID 32498288, 2020). "It has been reported in previous studies that miR-101/EZH2 is expressed abnormally in a variety of tumors, including prostate cancer, bladder cancer, gastric cancer and glioma." (PMID 31966062, 2020). "Beyond silencing gene expression via its histone methyltransferase activity, EZH2 can directly coactivate the androgen receptor and other transcription factors in prostate cancer." (PMID 32143573, 2020). "We confirmed the endogenous interaction between EZH2 and USP7in the metastatic prostate cancer cell line DU145." (PMID 32453339, 2020). "While other specific targets of EZH2 in uterine tissue remain to be determined, gene targets of EZH2 in breast, and prostate cancer cell types have been reported." (PMID 33732505, 2020). "To further validate the pathological relevance of such connection, we set out to determine the HNF1B expression pattern, and its relationship with EZH2 level in prostate cancer samples." (PMID 31636385, 2020). "In this study, we used PCA to distinguish the main factor among EZH2, TROAP and E2F1 causing tumorigenesis and development of prostate cancer." (PMID 33692939, 2020). "In our previous study, we have shown that HNF1B can diminish the effect of EZH2 in promoting prostate cancer proliferation." (PMID 33174391, 2020). "For example, NTN3 is regulated by AR and EZH2 in prostate cancer, and also acts in the activation of the hormone ER pathway." (PMID 32251318, 2020). "In concordance with those, we have found that the expression of EZH2 on an immunohistochemical and mRNA level is statistically significantly higher in prostate carcinoma compared to adenomyomatous hyperplasia samples." (PMID 32873863, 2020). "Instead of transcriptional repression EZH2 target gene expression, pS21-EZH2 serves as a transcriptional co-activator in castration-resistant prostate cancer through PI3K/AKT signaling." (PMID 33308321, 2020). "It has been reported that EZH2 promotes prostate cancer progression and metastasis via facilitating cell growth, proliferation, and migration." (PMID 31636385, 2020). "Recently,we reported the deubiquitinating activity of USP44 and the subsequent stabilizationof EZH2 protein in prostate cancer cells (Parket al., 2019)." (PMID 32453339, 2020). "Collectively, these results indicate that the promotion of cellmigration, invasion, and sphere formation by USP7 is partly attributable to thestabilization of EZH2 in prostate cancer cells." (PMID 32453339, 2020). "Accumulating evidence has shown that EZH2 expression level correlates with the advanced stages of prostate cancer progression and poor prognosis, and its oncogenic function is required for prostate tumorigenesis." (PMID 31636385, 2020). "Although the study was based on RNAi and overexpression approaches, our findings call for future investigation of EZH2 inhibitors in treating tumors, including prostate cancer, with low HNF1B expression mediated by EZH2 overexpression." (PMID 31636385, 2020). "In previous study, we have identified HNF1B as a transcriptional target of EZH2 that can rescue EZH2‐mediated migration and cell growth in prostate cancer." (PMID 33174391, 2020). "Recent researches have also confirmed that EZH2 plays an important role in the advanced stages of prostate cancer, including CRPC and neuroendocrine prostate cancer (NEPC)." (PMID 31636385, 2020). "EZH2 can promote the development and evolution of prostate cancer by regulating HK2-mediated tumor anaerobic glycolysis." (PMID 33299646, 2020). "Overexpression of enhancer of zeste homolog 2 (EZH2), the major histone H3 lysine 27 methyltransferase, has been connected to prostate cancer malignancy." (PMID 31636385, 2020).
prostate carcinoma (continued). "In prostate cancer cells, Asangani found that EZH2 catalyzes H3K27 trimethylation to inhibit miR-26a, miR-31, and miR-203, which target the 3’-UTR of NSD2." (PMID 33665162, 2020). "We have determined that EZH2 inhibitors can suppress prostate cancer lineage plasticity, neuroendocrine transformation, and resistance to androgen receptor targeted therapies in pre-clinical mouse and human experimental models." (PMID 32292420, 2020). "GSK926 and GSK343 can suppress histone H3K27me3 level and inhibit EZH2 activity in breast and prostate cancer cells, while GSK343 can only be used in vitro due to the high clearance in rat PK studies." (PMID 32723346, 2020). "HNF1B suppresses EZH2‐mediated migration of two prostate cancer cell lines via represses the EMT process by inhibiting SLUG expression." (PMID 33174391, 2020). "As target gene of BRG1, EHF has been shown to contribute to differentiation and proliferation of epithelial cells, as well as EZH2 expression, and apoptotic signaling regulation in prostate cancer stem cells." (PMID 33070167, 2020). "In preclinical studies, various EZH2 inhibitors like GSK-126/343/503 that targets EZH2 enzyme activity demonstrated growth inhibition in prostate cancer cell lines." (PMID 35582225, 2020). "EZH2 functions to regulate actin polymerization dynamics, indicating a role in promoting motility or invasiveness of prostate cancer cells." (PMID 33327550, 2020). "For instance, MALAT1 was reported to bind EZH2 and further enhance histone 3 lysine 27 trimethylation (H3K27me3) levels at the target gene loci of EZH2 in prostate cancer cell lines." (PMID 32972446, 2020). "EZH2 inhibitor has been extensively explored in various cancers recently, while its implication in prostate cancer has been controversial." (PMID 31636385, 2020). "The expression of other miRNAs, such as miR-338-5p and miR-421, were proposed to be epigenetically silenced by EZH2 in prostate cancer, although in a H3K27me3 analysis, remained undetermined." (PMID 33291485, 2020). "For example, lncRNA FOXC2-AS1 accelerated the tumor progression of prostate cancer cells by regulating the proliferation and tumor growth through miR-1253/EZH2 axis, thus leading to the poor prognosis of prostate cancer patients." (PMID 33292272, 2020). "Until now, only a few target genes have been studied in depth to clarify the regulatory network of EZH2 in prostate cancer, including CDH1, DAB2IP, ADRB2." (PMID 31636385, 2020). "Such binding events of EZH2 were then confirmed by ChIP-qPCR in another prostate cancer cell line, DU145." (PMID 31636385, 2020). "EZH2 expression is significantly elevated in prostate cancer and is accompanied with accelerated proliferation and enhanced metastasis capability." (PMID 31636385, 2020). "EZH2 binds HNF1B locus and suppresses HNF1B expression in prostate cancer cell lines, which is further supported by the reverse correlation between EZH2 and HNF1B expression in clinical samples." (PMID 31636385, 2020). "The tumor-promotingactivity of EZH2 in castration-resistant prostate cancer is mediated by its activityas a coactivator for AR." (PMID 32453339, 2020). "Next, we examined HNF1B and EZH2 expression in prostate cancer cell lines with different metastatic potentials." (PMID 31636385, 2020). "Forkhead box transcription factor-1 (FOXO1) is a tumor suppressor that is downregulated in human prostate cancer, which acts as a repression target of EZH2 and an essential mediator of EZH2 inhibition-induced cell death." (PMID 32264916, 2020). "In prostate cancer cells, the transcriptionalrepression function of EZH2 was inhibited by USP7-knockdown." (PMID 32453339, 2020). "Of note, we observed that EZH2 expression indeed tracked tightly with CENPA expression in prostate cancer tissue." (PMID 32371391, 2020). "In a prostate cancer study, the depletion of EZH2 inhibited prostate cancer cell growth and aerobic glycolysis accompanying the upregulation of miR-181b." (PMID 32723346, 2020).
prostate carcinoma (continued). "EZH2 was knocked down by a pool of small interfering RNAs (siRNAs) in C4-2 and 22Rv1 prostate cancer cell lines." (PMID 31410199, 2019). "As EZH2 is frequently overexpressed in human prostate cancers, it becomes a very attractive therapeutic target." (PMID 31410199, 2019). "The tumors developed in mice resembled the neuroendocrine variant of prostate cancer, expressing increased levels of epigenetic regulators SOX2 and EZH2." (PMID 31366128, 2019). "Most importantly, we identified FOXO1 as a key mediator of EZH2 inhibition-induced death of prostate cancer cells." (PMID 31410199, 2019). "As the key catalytic subunit of PRC2, EZH2 is widely overexpressed in many tumors, including prostate cancer." (PMID 32039001, 2019). "Similar results were gained by another research that MIR193A is downregulated in metastatic prostate cancer and is involved in HOTAIR/EZH2/miR-193a feedback loop to exert a tumor suppressive function in prostate cancer." (PMID 31523496, 2019). "For example, eHSP90 influences the activation of epithelial-to-mesenchymal transition (EMT) in prostate cancer cells by modulating the expression and activity of EZH2." (PMID 31163702, 2019). "Significant in vivo efficacy was reported when combining an EZH2 inhibitor with enzalutamide for treatment of a prostate cancer xenograft model." (PMID 31200487, 2019). "We recently demonstrated that conditioned media from prostate cancer cells expressing EZH2 shRNA or treated with GSK126 or EPZ6438 inhibit in vitro angiogenesis of endothelial cells." (PMID 32039001, 2019). "In the present study, we identify FOXO1 as a direct downstream target gene of EZH2 in prostate cancer and other cancer types." (PMID 31410199, 2019). "EZH2 protein level inversely correlated with FOXO1 protein expression in prostate cancer patient specimens." (PMID 31410199, 2019). "While several mechanisms have been proposed for the downregulation of FOXO1, our data uncover a novel mechanism whereby increased level of EZH2 in prostate cancer results in repression of FOXO1 expression." (PMID 31410199, 2019). "For example, lncRNA MALAT1 is highly expressed in prostate cancer, which promotes the development of prostate cancer by activating EZH2." (PMID 31123170, 2019). "This conclusion was confirmed through the analysis of a large set of prostate cancer biopsies showing that EZH2 expression correlates with Gleason score and lymph node metastases." (PMID 31366128, 2019). "miR-338-5p and miR-421 expression can be repristinated in SPINK1-overexpressing prostate cancers through epigenetic drugs affecting EZH2 expression or through synthetic mimics." (PMID 31366128, 2019). "Based on the increasing evidence for the role of EZH2 in prostate cancer progression, EZH2 inhibitors are being evaluated in CRPC patients, as well as in other cancers." (PMID 31366128, 2019). "This is different from other tumor models, such as in myc-driven prostate cancer, in which EZH2 knockdown restored IFNGR1 expression and further led to activation of IFN-JAK-STAT1 signaling." (PMID 31727135, 2019). "Increased expression of the H3K27 histone methylase enhancer of zeste homolog (EZH2) gene is a common feature of advanced prostate cancer and NEPC and is observed both in patients and in tumor models." (PMID 31200487, 2019). "The histone methyltransferase enhancer of zeste 2 (EZH2) is an epigenetic modifier frequently overexpressed in many cancer types including prostate cancer and supports cancer cell proliferation and survival." (PMID 29921838, 2018). "Overexpression of EZH2 was as well reported in prostate cancer and is suggested to be involved in tumor progression." (PMID 29615825, 2018). "In several prostate cancer cell lines, overexpressing EZH2 represses TSP1, while suppressing EZH2 with inhibitors or shRNA induces TSP1." (PMID 30287808, 2018).
prostate carcinoma (continued). "The authors show that Ezh2 inhibition restores enzalutamide sensitivity in NEPC variants and recurrent prostate cancer cells by opposing lineage transformation [63••]." (PMID 29888169, 2018). "Here the authors show that ADT activates CREB that acts by increasing EZH2 activity to promote neuroendocrine differentiation in prostate cancer, providing alternative avenues for therapy." (PMID 30287808, 2018). "TSP1 is downregulated in advanced prostate cancer patient samples and negatively correlates with NE markers and EZH2." (PMID 30287808, 2018). "So far we have shown that the CREB/EZH2 axis is important for neuroendocrine phenotypes of prostate cancer cells." (PMID 30287808, 2018). "Future studies are warranted to investigate the contributions of the CREB/EZH2/TSP1 pathway shown here in prostate cancer cells to the lineage plasticity of lung cancer cells." (PMID 30287808, 2018). "Silencing EZH2 expression by shRNA in prostate cancer cells abrogates ISO-induced tube formation of SVEC4-10 endothelial cells." (PMID 30287808, 2018). "Another mechanism through which HIF-1α can increase EZH2 expression has been demonstrated in prostate cancer cells." (PMID 30510924, 2018). "In conclusion, hypoxic condition in prostate cancer induces the expression of EZH2 and miR-93, which initiates H3K27me3 in TGFBR2 promoter and microRNA-induced silencing of target gene respectively." (PMID 29699590, 2018). "Enhanced levels of EZH2 protein expression and EZH2 catalytic activity play a crucial role both in murine models overexpressing N-Myc and in human castration-resistant prostate cancer cells." (PMID 30053872, 2018). "In prostate cancer, miR-181a, miR-181b, miR-200b, miR-200c, and miR-203 were found epigenetically repressed by EZH2." (PMID 29401683, 2018). "miR-26a influences cell cycle progression in Burkitt’ lymphoma cell lines by targeting EZH2, while miR-101 attenuates cell proliferation in bladder transitional carcinoma and prostate cancer cell lines." (PMID 29401683, 2018). "Similar correlations between NE markers, TSP1 and EZH2 are observed in other prostate cancer datasets, such as TCGA, SU2C40, FHCRC41 prostate cancer datasets." (PMID 30287808, 2018). "Epigenetic markers provide us important clues to identify critical modulators, the relatively common epigenetic marker H3K27me3 in human prostate cancer cell lines imply the involvement of H3K27 enzyme EZH2." (PMID 29699590, 2018). "EZH2 overexpression has been previously correlated with increased promoter methylation across numerous tumor types in prostate cancer, small-cell lung cancer, and clear cell sarcoma of the kidney." (PMID 30469511, 2018). "The involvement of H2AZ and EZH2 in prostate cancer and the reported down regulation of AR gene by metformin prompted us to further analyze the role of this drug in these two important epigenetic components." (PMID 30651935, 2018). "Taken together, we elucidate a new critical pathway, consisting of CREB/EZH2/TSP1, underlying ADT-enhanced NED and angiogenesis during prostate cancer progression." (PMID 30287808, 2018). "GSK926 and GSK-343 are also exhibited to inhibit EZH2 activity to suppress H3K27me3 level in breast and prostate cancer cells." (PMID 29556394, 2018). "In fact, normally, expression of miR-101 inhibits EZH2 production and the invasiveness of prostate cancer cells." (PMID 30510924, 2018). "ANCCA, a co-activator of androgen receptor (AR), can bind E2F and enhance E2F-mediated EZH2 transcription in prostate cancer cells." (PMID 29556394, 2018). "We tested the impact of GSK-J4 and DZNeP, chemical inhibitors of JMJD3 and EZH2 respectively on prostate cancer cell lines." (PMID 29805743, 2018). "The effect of metformin treatment on the levels of H2A.Z, EZH2 and H3K27me3 in prostate cancer cells (LNCaP, C4-2, and PC-3) and in normal (RWPE-1) cells was examined by western blotting." (PMID 30651935, 2018).